IL4 (interleukin 4)
Diseases named in the same sentence as IL4 in open-access papers (continued):
Sharing a sentence is not in itself a finding about the gene and the disease.
COVID-19 (continued). "Both single-cell immune response (endogenous signaling and signaling response to IFNα/IL-2/IL-4/IL-6 and LPS/CL097; factor 10) and plasma proteome (factor 3) data contributed strongly to the variance observed in our samples and were significantly associated with COVID-19 severity." (PMID 35839768, 2022). "Furthermore, a clear clustering of cytokines (IL-6, TNF-α, IFN-γ, IFN-α, SDF-1α, MIP-1α, MIP-1β, G-CSF, IL-10, CX3CL1 and IL-4) was observed in a PCA for critically ill COVID-19 patients during the first wave who presented a bacterial superinfection during their stay at the ICU." (PMID 35007290, 2022). "Interestingly, while many of these cytokines and chemokines were also elevated in SARS and MERS patients, several studies have reported an increase in Th2-related anti-inflammatory cytokines IL-4 and IL-10 in COVID-19 patients, ascribing a seemingly unique cytokine profile to COVID-19." (PMID 34452323, 2021). "In this study, the levels of TNF-α, IL-1α, IL-4, IL-6, IL-8, and IL-10, were measured through ELISA in sera from healthy volunteers as a control group, patients with moderate COVID-19, patients with severe COVID-19, and patients who had recovered from COVID-19." (PMID 33914789, 2021). "In this work, the IL-4 lung tissue expression was higher in most of the COVID-19 patients since the beginning of the aggravated disease despite the time from hospitalization to death and mechanical ventilation, suggesting that these mechanisms could be considered." (PMID 33122784, 2020). "Additionally, studies have documented high levels of some TH2 immune cells in COVID-19 patients (e.g. IL-4 and IL-10); although it has been suggested that these represent normal immune responses to SARS-CoV-2 tissue damage geared toward regulating inflammation and repairing tissue." (PMID 33235797, 2020). "It is unclear whether a fraction of the IL4-expressing cells found in the alveolar septa are represented in the single-cell RNA sequencing profiles generated from peripheral blood mononuclear cells of COVID-19 patients." (PMID 33042157, 2020). "In serum samples, soluble TLR-2 and TLR-4, IL-1β, IL-4, IL-6, Il-10, IFN-α, and TNF-α levels were significantly decreased in patients with coronavirus disease-19 (COVID-19) as compared with other viruses (p < 0.05 in each)." (PMID 41766850, 2026). "In the first phase of the study, participants in the acute phase of COVID-19 presented patterns of elevated inflammation in the form of high concentrations of cytokines such as TNF (TNF–α), LTA (TNF–β), IL–1β, IL–4, IL–6, IL–8, IL–13, and interferon (IFN) –α2." (PMID 40217938, 2025). "Cytokine concentrations (IFN-γ, IL-1Ra, IL-4, IL-6, IL-9, IL-13, and TNF-α) were higher in the breast milk from the breastfeeding mothers with symptomatic and asymptomatic COVID-19 compared with the control group at both sampling times." (PMID 40141241, 2025). "Breastfeeding mothers with symptomatic or asymptomatic COVID-19 presented higher levels of several cytokines, such as IFN-γ, IL-4, IL-6, and TNF-α, compared to control groups." (PMID 40141241, 2025). "Supervised machine learning algorithm (RF) was used to predict the COVID-19 severity and chronicity based on immune subset profiling and a 14-plex cytokine panel (TNF-a, IL-4, IL-13, IL-2, GM-CSF, sCD40L, CCL5, CCL3, IL-6, IL-10, IFN-g, VEGF, IL-8, and CCL4." (PMID 40657638, 2025). "None of the other measured mediators related to eosinophils and the T2 response (CCL26, IL-3, IL-4, IL-5, CD44, TSLP, or GM-CSF) displayed any significant differences between the different timepoints and between COVID-19 versus controls." (PMID 40710346, 2025). "COVID-19 exhibited a distinct immunological profile characterized by increased levels of Th1 (IL-12 and IFN-γ) and Th2 (IL-4, IL-5, IL-10, and IL-13) cytokines, along with IL-1β and IL-6, among other markers." (PMID 39408907, 2024). "As patients recuperate from COVID-19, cytokine levels including TNF-α, TGF-b, IFN-g, IL-1b, IL-2, and IL-4 subside." (PMID 38844850, 2024).
COVID-19 (continued). "PLWH with COVID-19 with a detectable VL had significantly lower concentrations of IL-2, IL-4, IFN-γ, IL-20, IL-22, IL-35, and IL-12p40 than PLWH with COVID-19 with an undetectable VL." (PMID 39597537, 2024). "In contrast, the Th2 cytokines IL-4 and IL-10 were moderately increased, suggesting the CD4 + T cell lineage is skewed towards Th2 in COVID-19." (PMID 38389037, 2024). "The present study highlights the dynamic interplay between IFN-γ and IL-4 between Th1 and Th2 immune responses, with IFN-γ as a critical indicator of immune dysregulation during COVID-19." (PMID 39408907, 2024). "GMCSF, IL-13, IL-1β, IL-2, IL-4, and IL-5 were undetectable in the vast majority of both TTP and COVID-19 samples." (PMID 39337495, 2024). "We also observed COVID-19-specific enrichment of signaling genes such as MAP3K1, which helps activate JNK and ERK pathways, and STAT6, which is involved in IL-4 and IL-13 signaling." (PMID 36992700, 2023). "Reelin level was correlated with IL-1α, IL-4, IP-10, MIP-1β, and ICAM-1, suggesting a specific role for Reelin in COVID-19 progression." (PMID 37441066, 2023). "Severe patients (n = 6) showed a significant increase in a subset of plasma cytokine/chemokine levels (IL-2, IL-4, IL-6, IL-8, MIP-1β, and TNF-α; ANOVA, p adjusted <0.05 to <0.001) in comparison with the pauci COVID-19 patients (n = 8) and/or controls." (PMID 37047752, 2023). "Most notably, PBMCs from COVID-19 patients were enriched in JAK-STAT and IL-4 signaling, which has been known to drive inflammation following infection." (PMID 36992700, 2023). "The potential pathway through which dupilumab helps patients recover from COVID-19 might be that dupilumab restricts the duplication of SARS-CoV-2 and alleviates the abnormal immune responses in AD patients, possibly by blocking the augmented reaction caused by IL-4 and IL-13." (PMID 37240520, 2023). "As reported in our prior study, at 13 months after discharge, 11.6% of the HCWs with severe COVID-19 had elevated IL-6, and more than 98% had normal levels of the remaining five cytokines (IFN-γ, IL-10, IL-2, IL-4 and TNF-α)." (PMID 36908474, 2023). "The aim of this study was to evaluate a COVID-19 vaccine allergy using in vitro T-cell exposure to the tested drug with the flow cytometry measurement of CD69, CD40L, TNFa, IFNG, IL-2, IL-4, IL-6, IL-10, intracellular granulysin, and IFNgamma." (PMID 37686102, 2023). "We found that the levels of IL-4, IL-6, IL-8, IL-12, TGF-β, and TNF-ɑ related pathways were upregulated in COVID-19 brains compared with control brains." (PMID 36609561, 2023). "Previously, our group has shown an increased level of cytokines in the antigen-specific culture supernatants including IFNγ, IL-2, IL-4, IL-13, and IL-17 in MIS-C in comparison with acute COVID-19 and other infectious diseases." (PMID 38116577, 2023). "The RS between activation marker concentrations and the severity of COVID-19 are calculated by training data set Z2KP, where the activation markers are IL-17a, IL-2, GATA3, IFN-γ, IL-4, IL-10, PD_1, CD40L, RORγt, CTLA_4, CCR7, TNF-α and IL-6, respectively." (PMID 36845115, 2023). "Reelin level was highly correlated with IL-1α, IL-4, IP-10, MIP-1β, and ICAM-1, suggesting a specific role for Reelin in COVID-19 progression." (PMID 37441066, 2023). "COVID-19 patients with ARDS exhibited higher serum levels of all cytokines and chemokines measured (IFNy, TNFa, IL-4, IL-6, IL-7, IL-8, IL-10, IL-13, MIP-1b, and MCP-1) compared to patients with COVID-19 pneumonia without ARDS (data not shown)." (PMID 37293294, 2023). "Symptomatic COVID-19 patients had significantly (p < 0.05) higher levels of IL-10, IL-2, IL-2R, IL-6, IL-8 GM-CSF IP-10, TNF-α, IL-4, IL-5, IL-12, IFN-γ and MIP-1β compared to the asymptomatic cases." (PMID 36184636, 2022). "For example, the ratios of TNF-α/IL-5, IFN-α/IL-10, IL-6/IL-5, TNF-α/IL-4, and IFN- γ/IL-5, were lower (≈24-, 23-, 20-, 10-, and 10-fold) in COVID-19 ICU patients as compared with HC subjects." (PMID 36363785, 2022).
COVID-19 (continued). "Outbreaks of COVID-19 are accompanied by immunocompromised through hyperexpression of both proinflammatory (IL-1, IL-2, IL-6, and TNF-α) and anti-inflammatory (IL-4, IL-10, and IL-17) cytokines, and vice versa with IFN-γ." (PMID 36045713, 2022). "On the other hand, serum levels of cytokines in COVID-19 ICU patients showed a significant increase in the production of GM-CSF, IFN-α, IL-2, IL-4, and IL-6 and a significant decrease in the levels of IFN-γ, IL-5, IL-12, IL-17A, and TNF-α." (PMID 36363785, 2022). "The SARS-CoV-2 spike protein enhanced the expression of ACE2 in Beas-2B cells, and the cytokines IL-4 and IL-13 were repressed, whreas TNF-α, IL-12, and IL-17 increased ACE2 expression in Beas-2B cells, which reflects the different risks of severe COVID-19." (PMID 35287354, 2022). "Patients with COVID-19 showed a significant positive correlation (p < 0.001) between their CO-RADS score and their WBCs, CRP, and interleukins (IL-1, IL-4, IL-6, IL-18, and IL-35) levels." (PMID 36675695, 2022). "MMP-7, TGF-β, CCL2, CCL-3, CXCL-10, G-CSF, IFN gamma, IL-10, IL-2, IL-4, IL-6, IL-7, TNF-α, IL-6, and IGF-1 were studied for their correlation to lung involvement in COVID-19 patients." (PMID 36286038, 2022). "In COVID-19 patients, high levels of TNF-α, IL-1β, IL-4, IL-6, IL-10, IP-10, MCP-1, and MIP-1A have been detected, and particularly, high IL-6 concentrations are positively correlated with the severity of the disease." (PMID 35744777, 2022). "In the multiplex cytokine assays, plasma levels of Th2-related soluble factors such as IL-4, IL-5, IL-13, and CCL22 were comparable between the patient with COVID-19 mRNA vaccine-related myopericarditis and healthy controls." (PMID 35251049, 2022). "IL-6, IL-8, IL-10, and TNF-α were increased in severe cases of COVID-19 while IFN-α, IL-1β, IL-4, and IL-15 were enriched in mild cases." (PMID 35685940, 2022). "Serum levels of EGF, G-CSF, GM-CSF, IL-1ra, IL-1α, IL-1β, IL-2, IL-4, IL-7, IL-8, EOTAXIN, fractalkine, GRO, P-10, MDC, MIP-1α, MIP-1β, IFNα2, and sCD40L were significantly lower in female COVID-19 patients compared to controls." (PMID 36554094, 2022). "Data analysis demonstrated an increased order of magnitude (≥3x) for CXCL8, CCL3, IL-6, IFN-γ, G-CSF and decreased order of magnitude (≤0.3x) for CCL11, IL-4, IL-5, IL-10, PDGF and IL-7 in COVID-19 patients throughout the kinetic follow-up." (PMID 36451835, 2022). "In this study concentrations of TNF-α, IL-1b, IL-2, IL-4, IL-5, IL-6, IL-8, IL-10, IL-12 p70, GM-CSF, and IFN-γ were determined by a magnetic bead assay in tear film collected from 232 symptomatic COVID-19 patients." (PMID 35508669, 2022). "Our results demonstrate that melatonin consumption for 14 days significantly decreases plasma levels of IL-4, IL-2, IL-1β, IFN-γ, and IL-6 in COVID-19 patients." (PMID 36254292, 2022). "In male participants, EGF, GM-CSF, IL-1ra, IL-1α, IL-1β, IL-2, IL-4, IL-7, IL-15, EOTAXIN, MDC, MIP-1α, MIP-1β, IFNα2, and sCD40L were significantly lower in COVID-19 patients compared to controls." (PMID 36554094, 2022). "The ratios of IFN-γ/IL-4, IL-12/IL-4, IFN- γ/IL-9, TNF-α/IL-4, IFN- γ/IL-5 and IL-12/IL-9 were lower ((≈30-, 11-, 8, 4-, 4-, and 3- fold differences respectively) in COVID-19 ICU patients as compared to HC subjects." (PMID 36363785, 2022). "Previously, it was shown that CD8+ Tc1 cells able to produce IFNγ, similar to Tc2 (CD8+IL-4+) and Tc17 (CD8+IL-17A+) cells, were lowered in convalescent COVID-19 patients compared to control subjects." (PMID 36146713, 2022). "In this study, a considerable rise in serum LDH, troponin I, CK-MB, IL-1β, IL-4, IL-10, IL-17, and INF-γ levels was recorded in COVID-19 patients compared to healthy controls." (PMID 35891209, 2022). "Of the 16 mediators elevated in early COVID-19 compared with healthy controls, 11 decreased over time (CCL3, CCL4, TNF-α, IL-6, CCL13, IL-4, IFN-α2a, CXCL10, CXCL11, IL-2, and IL-12)." (PMID 35397798, 2022).
COVID-19 (continued). "MMP-7, TGF-β, CCL2, CCL-3, CXCL-10, G-CSF, IFN gamma, IL-10, IL-2, IL-4, IL-6, IL-7, TNF-α, IL-6, and IGF-1 were studied for their correlation with mortality in all 40 COVID-19 patients." (PMID 36286038, 2022). "Meanwhile, COVID-19 displayed an immune profile distinguished by increased Th1 (IL-12, IFN-γ) and Th2 (IL-4, IL-5, IL-10, IL-13) cytokine levels, along with IL-1β, IL-6, CCL11, VEGF, TWEAK, TSLP, MMP-1, and MMP-3." (PMID 33995342, 2021). "Relative to healthy controls, low levels of IL-4, IL-1RA, GRO and VEGF, and high levels of IL-2 in nasal lining fluid, were confined to PCR-confirmed COVID-19 and PCR−/IgG+ SARI participants." (PMID 34117221, 2021). "Since a cytokine storm is one of the complications of COVID-19, some of the MAbs are also targeted against proinflammatory mediators, such as TNF-α, IL-4, and IL-10." (PMID 34769383, 2021). "It remains to be defined why COVID-19 patients had severe and critical clinical characteristics independent of circulating levels of inflammatory cytokines (IFN-γ, TNF-α, IL-2, IL-4 and IL-10)." (PMID 34123873, 2021). "When comparing the COVID-19 to the H1N1 group, statistically increased tissue immunoexpression of ACE-2 (p = 0.0005), CD44v6 (p < 0.0001), IL-4 (p < 0.0001), and α-SMA (p < 0.0001) were observed in the former." (PMID 35008594, 2021). "In contrast, IL-1β, IL-4, IL-5, IL-12p70, IL-13, IL-17A, CCL11, and VEGF levels predicted severe COVID-19." (PMID 33995342, 2021). "Other researchers also reported elevated levels of IL-2, IL-4, and INF-γ in patients with COVID-19 31, 32, and that these levels were highly correlated with disease progression." (PMID 33967617, 2021). "There was also a significant increase observed in the immunoexpression of tissue biomarkers ACE-2, AKT-1, CD44v6, IL-4, MMP-9, α-SMA, Sphingosine-1, and TGF-β1 in the COVID-19 group." (PMID 35008594, 2021). "The majority of COVID-19 patients had normal levels of TNF-α (40/52, 76.9%), IL-2 (47/52, 90.4%) and IL-4 (36/52, 69.2%)." (PMID 34123873, 2021). "Levels of pro-inflammatory (IFN-γ, IL-1β, IL-6, IL-9, IL-12p70, CCL11) and anti-inflammatory (IL-4, IL-5, IL-10, IL-13) cytokines, as well as VEGF, were higher in severely ill COVID-19 patients as compared to pandemic influenza A(H1N1) subjects." (PMID 33995342, 2021). "Our present results identified obvious elevations of various cytokines in patients with severe COVID-19, including IL-1α, IL-1β, IFN-γ, TNF-α, IL-2, IL-4, IL-6, IL-10, and IL-17A." (PMID 34113636, 2021). "In the COVID-19, Th1 cells were significantly higher than Th2 CD4+ T cells, which produced IL-4, IL-2, and TNF, main markers for Th2 response." (PMID 34571855, 2021). "Evaluation of cytokines at week 2 revealed that the levels of IL-4, IL-6, IL-10, and IFN-γ were higher, while the levels of IL-2 were lower in COVID-19 patients than that in HC." (PMID 33390771, 2021). "We found that the lung CTs of patients with moderate or severe pneumonia due to COVID-19 were more likely to have GGO if they had increased levels of IL-2, IL-4, and INF-γ, and that IL-2 was significantly and independently associated with GGO." (PMID 33967617, 2021). "In patients with severe COVID-19, we found that TNF-α was satisfactorily correlated with IL-2, IL-4, and IFN-γ, and monocytes were negatively correlated with IL-2, IL-4, and TNF-α." (PMID 34712741, 2021). "Meanwhile, expression of IRF4 is associated with the secretion of IL-4 and IL-10 which are anti-inflammatory cytokines that may be important to reduce the damage of the cytokine storm in moderate patients and not develop in severe COVID-19 symptoms." (PMID 34603282, 2021). "Results showed that COVID-19 patients have higher serum level of cytokines (TNF-α, IFN-γ, IL-2, IL-4, IL-6 and IL-10) and CRP than control individuals." (PMID 32475230, 2020). "There are higher levels of inflammatory factors, including IL-2, IL-4, IL-6, IL-10, TNF-α, and IFN-γ, found in COVID-19 patients than in healthy people." (PMID 32985562, 2020).
COVID-19 (continued). "Higher prepandemic concentrations of IL-2R, IL-4 and IL-5 protected against COVID-19, but not against SARS-CoV-2 infection." (PMID 40910046, 2025). "Interestingly, quickly discharged COVID-19 patients have a strong STAT signaling response in peripheral blood mononuclear cells, including pSTAT6,67 the STAT that is specific to IL-4 signaling." (PMID 40854598, 2025). "The presence of chronic inflammation in hypertensive patients may explain our observation of increased circulating levels of IL-4, IL-5, IL-13, IL-17A, and TNF-β levels during hospitalization in patients with COVID-19 and hypertension in the present study." (PMID 39685774, 2024). "According to our findings, IL-4 was also elevated in the appendixes of children with COVID-19 compared to acute appendicitis and appendixes during non-pandemic periods." (PMID 38397914, 2024). "Previous studies have explored the correlation between serum levels of pro-inflammatory (IL-2, IFN-γ, TNF-α) or anti-inflammatory cytokines (IL-4 and IL-10) with clinical or negative outcomes in individuals with COVID-19." (PMID 38601541, 2024). "COVID-19 is characterized by increased interferon-γ (IFN-γ) and IL-1β, IL-4, and IL-10 production." (PMID 38131979, 2023). "Simultaneously assayed anti-spike T cells producing IL-4 or IL-10 were minimal for vaccinees, whereas several COVID-19-recovered persons exhibited IL-4 but not IL-10 responses of unclear significance." (PMID 36860850, 2023). "Cytokines unique to COVID-19 cocktails (IL-4, IL-13), but not sACE2, induced mild albuminuria when injected alone in BALB/c mice." (PMID 37040185, 2023). "Previous studies found increased the Th2 cytokine profile (i.e., IL-4 and IL-15) and IL-10 in the blood of recovered mild COVID-19 patients without sequelae." (PMID 37753077, 2023). "In addition, it has been reported that in COVID-19 patients, the virus activates apoptosis by stimulating JAK-STAT6 signaling pathway through increased Th2 and IL-4 expression." (PMID 36851291, 2023). "There is also an important number of Th2R and IL-4+IL10+ Tr cells that could explain both the increase of Th2 cells and IL4 and IL10 in severe COVID-19." (PMID 36678366, 2022). "Consistent with the current findings, several previous studies have demonstrated that serum IL-4 levels are not increased in critical COVID-19 patients however, contradictory evidence also exists." (PMID 36045688, 2022). "Additionally, IL-4, IL-12, IL-2, CXCL10, platelet derived growth factor subunit A (PDGFA), and IFN-α2a kinetic changes were similar between the natural course of early COVID-19 and inhaled budesonide." (PMID 35397798, 2022). "Another immune signature detected in critically ill patients with COVID-19 includes the type 2 cytokines IL-4, IL-5, IL-13, and TSLP, related to noninfectious lung diseases (Choreño-Parra and others 2021)." (PMID 35647937, 2022). "In relation to individuals in the post-COVID-19 group, higher levels of IL-10 and IL-4 were observed in the group that did not present sequelae after the disease." (PMID 35846757, 2022). "Previous reports on immune response to SARS-CoV-2 have shown that T cell response is greatly diverse, as T cells from COVID-19 patients can secrete TH1 cytokines, including IFN-γ and TNF, TH17 cytokines, including IL-17A, TH2 cytokines, including IL-4, and others, including IL-2 and CD107a." (PMID 35386702, 2022). "In addition, the analysis of lung tissue biopsy samples from patients with COVID-19 identified an increase in CD117+ mast cells and IL-4-expressing cells in the perivascular space and alveolar septa compared to controls." (PMID 35632823, 2022). "In addition, cytokines in COVID-19 patients, including IFN-γ, IL-2, and IL-4 were observed to decrease compared to levels in HCs." (PMID 35422810, 2022). "Interestingly, early in COVID-19, there is also a Th2 immune response, mediated mainly by CCL11 and IL-4." (PMID 35397798, 2022).